SKP2 (S-phase kinase associated protein 2)
Diseases named in the same sentence as SKP2 in open-access papers (continued):
Sharing a sentence is not in itself a finding about the gene and the disease.
breast carcinoma (continued). "SKP2 promotes programmed cell death protein 4 degradation through phosphorylation and ubiquitination, resulting in increased proliferation and radiation tolerance of breast cancer cells." (PMID 34925455, 2021). "Formation of the E-cadherin/AhR/Skp2 complex and subsequent ubiquitination of E-cadherin induced by kynurenine has been documented in lung cancer and breast cancer cells, indicating a generalized mechanism of E-cadherin suppression by kynurenine in different cancer types." (PMID 34769098, 2021). "Indeed, a role of SKP2 in regulating cell metabolism has been recently highlighted in breast cancer and warrants future studies during leukemogenesis." (PMID 31772299, 2020). "To test whether diosgenin performed anticancer activity via regulation of the Skp2 signaling pathway in breast cancer cells, we conducted the rescue experiment to observe if overexpression of Skp2 would abrogate diosgenin-induced antitumor function." (PMID 32626765, 2020). "Genistein can induce apoptosis in BRCA wild-type-1 and mutant BRCA cancer cells, induce apoptosis in breast cancer cells by reducing the level of expression of miR-155, micro-RNA, has the potential to inhibit Skp2 expression in breast cancer cells as an anticancer effect." (PMID 33005774, 2020). "Our findings revealed that diosgenin could be a potential inhibitor of Skp2 for treating breast cancer." (PMID 32626765, 2020). "Importantly, Skp2 upregulation rescued inhibition of cell viability induced by diosgenin in both breast cancer cell lines." (PMID 32626765, 2020). "Skp2 oncoprotein has been characterized to participate in carcinogenesis, including breast cancer." (PMID 32626765, 2020). "Since Skp2 is an important oncoprotein in breast cancer development, we performed multiple experiments to determine whether diosgenin inhibits the expression of Skp2 in breast cancer cells." (PMID 32626765, 2020). "Moreover, Skp2 plays an oncogenic role via promotion of cell proliferation, migratory and invasive activity, metastasis, and drug resistance in breast cancer." (PMID 32626765, 2020). "Altogether, diosgenin exerts its anticancer function via suppression of Skp2 in breast cancer." (PMID 32626765, 2020). "Since Skp2 is a key oncoprotein in human breast cancer, we tested whether diosgenin would downregulate the expression of Skp2 in breast cancer cells by RT-PCR and western blotting analysis." (PMID 32626765, 2020). "Moreover, upregulation of Skp2 inhibited cell apoptotic death and abrogated induction of cell apoptosis by diosgenin in two breast cancer cell lines." (PMID 32626765, 2020). "We found that diosgenin decreased the expression of Skp2 in breast cancer cells, suggesting that diosgenin could be a useful compound to treat breast cancer patients via targeting Skp2." (PMID 32626765, 2020). "Furthermore, reduction of Skp2 decreased cell invasive activity in two breast cancer cell lines, which further enhanced reduction of cell invasion mediated by diosgenin." (PMID 32626765, 2020). "Notably, diosgenin reduced cell viability and motility and induced apoptosis via suppression of Skp2 in breast cancer cells." (PMID 32626765, 2020). "Moreover, Skp2 downregulation stimulated cell apoptotic death in both breast cancer cell lines, which promoted diosgenin-mediated induction of apoptosis." (PMID 32626765, 2020). "To in-depth explore whether diosgenin exerts antitumor activity via modulation of Skp2 in breast cancer cells, we used Skp2 siRNA to reduce the Skp2 expression in breast cancer cells followed by diosgenin exposures for different times." (PMID 32626765, 2020). "For instance, USP18 was shown to promote breast cancer growth by activating the Skp2/AKT pathway." (PMID 32882786, 2020). "Furthermore, overexpression of Skp2 promoted cell invasion in breast cancer cells, which also rescued cell invasion suppression that was mediated by diosgenin treatments." (PMID 32626765, 2020).
breast carcinoma (continued). "Diosgenin inhibited both mRNA and protein levels of Skp2 in breast cancer cells." (PMID 32626765, 2020). "In this study, we aim to explore whether diosgenin performed antitumor activity via inhibition of Skp2 in breast cancer cells using several methods including MTT, Transwell invasion assay, RT-PCR, western blotting, and transfection." (PMID 32626765, 2020). "On the other hand, Ki-67 staining showed SKP2 knockdown reduced breast cancer cell proliferation in vivo and such suppression effect could be rescued by PDCD4 knockdown." (PMID 30760284, 2019). "SKP2 promotes breast cancer tumorigenesis and radiation tolerance via PDCD4 degradation." (PMID 30760284, 2019). "IHC staining in breast tumors revealed that SKP2 overexpression promoted breast cancer cell proliferation in vivo, as determined by Ki-67 staining, and such promotion effect could be rescued by PDCD4 overexpression." (PMID 30760284, 2019). "Radiotherapy combine with SKP2-targeted adjuvant therapy may improve breast cancer patient survival in clinical medicine." (PMID 30760284, 2019). "Thus, our data underscores the important role of the AMPK/Skp2 S256 phosphorylation/Akt axis in human breast cancer progression and disease outcome." (PMID 30413706, 2018). "The elevated penetrance of the Rb/SKP2 synthetic lethal effect in tumour cell models other than those derived from breast cancer suggested that this genetic dependency might operate in multiple histologies." (PMID 29915391, 2018). "Importantly, AMPK-mediated Skp2 S256 phosphorylation promotes breast cancer progression in mouse tumor models, correlates with Akt and AMPK activation in breast cancer patients, and predicts poor survival outcomes." (PMID 30413706, 2018). "Furthermore, qPCR showed that the mRNA expression of Skp2 and downstream genes, RhoA, was inhibited by treatment of both ER-positive and tamoxifen-resistant breast cancer cells with AC." (PMID 29743060, 2018). "Skp2 has been characterized as an oncoprotein in breast cancer." (PMID 27582552, 2016). "We discovered that rottlerin inhibited Skp2 expression in breast cancer cells." (PMID 27582552, 2016). "Moreover, overexpression of Skp2 promoted cell proliferation in breast cancer cells, whereas inhibition of Skp2 suppressed cell proliferation in MDA-MB-231 cells." (PMID 27582552, 2016). "Skp2 has been revealed to critically enhance the pathogenesis of breast cancer." (PMID 27582552, 2016). "Due to its oncogenic role in tumorigenesis, inhibition of Skp2 could be a promising therapeutic strategy for combating breast cancer." (PMID 27582552, 2016). "Our data validate that rottlerin inhibited Skp2 expression in breast cancer cells, indicating that rottlerin could function as a Skp2 inhibitor." (PMID 27582552, 2016). "Importantly, up-regulation of Skp2 rescued cell proliferation inhibition by rottlerin treatment in breast cancer cells." (PMID 27582552, 2016). "Next, we explored whether rottlerin could down-regulate Skp2 expression, leading to its anti-tumor activity in breast cancer cells." (PMID 27582552, 2016). "Our results indicated that rottlerin could inhibit Skp2 expression, leading to its anti-tumor function in breast cancer cells." (PMID 27582552, 2016). "Also, results are not consistent in breast cancer tissues and in pancreatic cancer tissues, although it can transcriptionally repress both expressions of the HER2 and Skp2 gene in the breast cancer." (PMID 27557492, 2016). "In the current study, we explore whether rottlerin could inhibit Skp2 expression, leading to inhibition of cell growth, migration and invasion in breast cancer cells." (PMID 27582552, 2016). "In the present study, we explored whether a nature agent rottlerin could be a potential inhibitor of Skp2 in breast cancer." (PMID 27582552, 2016). "Taken together, inhibition of Skp2 by rottlerin could be a promising approach for breast cancer treatment." (PMID 27582552, 2016).
breast carcinoma (continued). "We found that overexpression of Skp2 enhanced cell proliferation in both breast cancer cell lines." (PMID 27582552, 2016). "Our findings demonstrated that Skp2 is an oncoprotein in breast cancer and targeting Skp2 could be a useful approach for the treatment of breast cancer." (PMID 27582552, 2016). "Further study demonstrated that Skp2 triggered Akt activation in human breast cancer." (PMID 26046466, 2015). "Therefore, the extent of the functional dependency on SKP2 of different Cip/Kips proteins (p27, p21, and p57) in different breast cancer subtypes requires further study." (PMID 25530715, 2014). "Furthermore, Western blot and immunofluorescence microscopy analysis were used to study the relationship between expression of cytoplasmic PPARγ and Skp2 expression in human breast cancer cells in vitro." (PMID 23939428, 2013). "In addition, Skp2 overexpression can provoke cytoplasmic localization of PPARγ upon MEK1-dependent mechanisms in human breast cancer cells by nuclear-cytosolic fractionation technology and immunofluorescence microscopy analysis." (PMID 23939428, 2013). "Because Skp2 is located downstream in the MAPK signaling pathway, we have in the present study tested the hypothesis that Skp2 overexpression can provoke cytoplasmic localization of PPARγ upon MEK1-dependent mechanisms in human breast cancer cells." (PMID 23939428, 2013). "The fact that Skp2 expression was positive correlated with phospho-MAPK/ERK1/2 expression during progression of cervical neoplasia was in accordance with the study of human breast cancer progression." (PMID 23939428, 2013). "Overexpression of Skp2 has been reported in several human malignant tumors, including oral squamous cell carcinoma, ovarian adenocarcinoma, lymphoma, colorectal carcinomas, gastric carcinoma, soft tissue sarcomas, acute myelogenous leukemia, and breast cancer." (PMID 23939428, 2013). "Further, immunoblot analysis was carried out to evaluate the expression of p27, a pro-apoptotic cyclin D kinase inhibitor, which positively correlates with FOXP3 activity, and SKP2, a breast cancer oncogene known to be suppressed by FOXP3 transcriptional activity." (PMID 23341929, 2013). "Interestingly, in patients with low p-Akt1 expression, cytoplasmic Skp2 expression was significantly associated with DFS and OS of patients with breast carcinoma." (PMID 23300741, 2012). "Our results demonstrate that cytoplasmic Skp2 may facilitate not only progression, but also metastasis in breast carcinoma patients." (PMID 23300741, 2012). "However, the biological significance of cytoplasmic Skp2 expression and its prognostic significance are still undefined in breast cancer." (PMID 23300741, 2012). "Lastly, they proposed specific Skp2 inhibitors as novel anti-breast cancer agents." (PMID 23227454, 2012). "Furthermore, we observed an inverse correlation between Skp2 and E-cadherin expression in an array of breast cancer clinical samples." (PMID 23230084, 2012). "The Wei group recently summarized the oncogenic role of Skp2 in breast cancer development." (PMID 23227454, 2012). "Indeed, a correlation between elevated Skp2 protein expression and tumor metastasis has been noted in multiple tumors, including melanoma, lymphoma and breast carcinoma." (PMID 23230084, 2012). "SKP2 is overexpressed in a subset of breast carcinomas (ER- and HER2-) and might play a role in the development of resistance to anti-estrogens." (PMID 22309939, 2012). "However, we previously examined the effect of doxorubicin on Skp2 expression in various breast cancer cell lines." (PMID 18644126, 2008). "In the present study we examined the expression of p27Kip1 and Skp2 in patients with locally advanced breast cancers, before and after chemotherapy, in order to determine their potential roles as prognostic factors and as predictors of response to preoperative chemotherapy." (PMID 18644126, 2008).
breast carcinoma (continued). "The results of the present study suggest that Skp2 may be an accurate biological marker for prognosis as well as a predictor of response to doxorubicin-based chemotherapy in locally advanced breast cancer." (PMID 18644126, 2008). "Interestingly, the percentage of patients presenting with high Skp2 levels in locally advance disease was similar to that of patients presenting with high Skp2 levels in early breast cancer (40% and 42%, respectively)." (PMID 18644126, 2008). "Because Skp2 plays an important role in tumor progression in breast cancer and clinical outcome, these results suggest that rapamycin may be of benefit in cancers expressing high Skp2 levels." (PMID 16859513, 2006). "The results of the present study show that specific inhibition of the mTOR pathway by rapamycin may significantly down-regulate Skp2 levels in rapamycin-sensitive breast cancer cells." (PMID 16859513, 2006). "Thus, it was important to explore the mechanisms by which rapamycin down-regulates Skp2 expression in breast cancer." (PMID 16859513, 2006). "Rapamycin was found to stabilize p27 levels in breast cancer, but whether this effect is mediated through changes in Skp2 expression is unknown." (PMID 16859513, 2006). "Finally, we show here for the first time the possible involvement of the APC/C in the regulation of Skp2 abundance in breast cancer cells." (PMID 16859513, 2006). "Skp2 was recently found to be overexpressed in breast cancers, but the role of Cks1 in these cancers is unknown." (PMID 16168119, 2005). "Furthermore, in breast cancer, SKP2 reactivates AKT-mediated resistance to PI3K inhibitors." (PMID 38559562, 2024). "Skp2 may also promote PI3K inhibitor resistance in aggressive breast cancer cells." (PMID 38059614, 2024). "Therefore, inactivation of Skp2 in breast cancer might be a novel approach for fighting breast malignancy." (PMID 32626765, 2020). "Furthermore, diosgenin inhibited the expression of Skp2 in breast cancer cells." (PMID 32626765, 2020). "Therefore, it is essential whether diosgenin could decrease the expression of RhoA and stabilize Twist level due to Skp2 downregulation in breast cancer cells." (PMID 32626765, 2020). "We then explored whether SKP2 promotes breast cancer cells proliferation via PDCD4 suppression." (PMID 30760284, 2019). "However, the effect of AC on the expression of microRNA and Skp2 in ER-positive breast cancer and acquired tamoxifen-resistant breast cancer remain unclear." (PMID 29743060, 2018). "Moreover, up-regulation of Skp2 abrogated rottlerin-induced apoptosis in both breast cancer cells." (PMID 27582552, 2016). "Notably, Skp2 overexpression led to enhanced cell invasion in breast cancer cells." (PMID 27582552, 2016). "However, whether curcumin regulates SKP2 expression via this pathway in breast cancer remains unknown." (PMID 25530715, 2014). "The results of the present study thus expanded our knowledge of the PI3K/Akt-SKP2-Cip/Kips pathway and highlighted the critical implication of this pathway in overcoming the drug (curcumin) resistance that is commonly observed in different subtypes of breast cancer." (PMID 25530715, 2014). "FOXP3 acts as a transcriptional repressor of oncogenes, HER-2/ErbB2 and S-phase kinase-associated protein 2 (SKP2), and FOXP3-regulated microRNAs suppress special AT-rich sequence-binding protein 1, whereas deletions of FOXP3 exons extinguish those suppressive function in a breast cancer cell line." (PMID 24155921, 2013). "In breast cancer cells, Skp2 expression is associated with lack of estrogen receptor (ER) and HER-2, which is reflected by the elevated expression levels of Skp2 in the triple-negative breast cancer cell lines MDA-MB-468, and, to a lesser extent, MDA-MB-231, relative to ER-positive MCF-7 cells." (PMID 23071779, 2012). "Interestingly, recent data suggests that Skp2 expression may play a significant role in the etio-pathogenesis of a number of systemic malignancies besides breast carcinomas." (PMID 23087899, 2012).
breast carcinoma (continued). "Indeed, Skp2 has been found to be frequently overexpressed in a variety of human cancers including lymphomas, prostate cancer, melanoma, nasopharyngeal carcinoma, pancreatic cancer, and breast carcinomas." (PMID 23230084, 2012). "Skp2 expression may be a useful marker for predicting response to doxorubicin-based preoperative chemotherapy and clinical outcome in patients with locally advanced breast cancer." (PMID 18644126, 2008). "Whereas the role of Skp2 as an oncogene responsible for down regulation of p27Kip1 protein levels has been well established in a wide variety of cancers, the role of Cks1 in many of these cancers, and in particular breast cancer, is unknown." (PMID 16168119, 2005). "Thus, both Cks1 and Skp2 may be considered as potential novel prognostic markers and targets for the future development of specific therapeutic interventions in breast cancer." (PMID 16168119, 2005). "Both Skp2 protein and transcript levels were slightly decreased in our MRTF-null MEFs, and we note that in breast cancer cells, Skp2 expression also responds to mechanical cues via the YAP pathway." (PMID 41200793, 2025). "It has been reported that combination treatment with chrysin and 5 gg inhibits breast cancer cell proliferation in vitro and in vivo by downregulating phospho-LRP6 and Skp2 proteins." (PMID 37089937, 2023). "POU Domain Transcription Factor OCT4 mediates the tamoxifen resistance in breast cancer cells, and its expression is repressed by NK3 Homeobox 1(Nkx3-1), which is a substrate protein of Skp2." (PMID 37089937, 2023). "To further validate this regulatory axis in breast cancer, we assessed the correlation among the expression levels of these four proteins (FBXW2, pAKT, Moesin and SKP2) in HR positive breast cancer patients." (PMID 37736741, 2023). "In the breast cancer cell lines MCF-7 and MDA-MB-231, diosgenin downregulates the expression of Skp2 at both the mRNA and protein levels, thus decreasing breast cancer cell viability and invasion, as well as stimulating apoptosis." (PMID 37089937, 2023). "Paradoxically, in human breast cancer, LCK suppresses cellular invasion by decreasing MMP9, SKP2, and VEGF-A expression but promotes the metastasis of breast cancer." (PMID 36430477, 2022). "During liver and breast cancer development, HBXIP reportedly promotes tumor cell proliferation through transcriptional activation of crucial tumor oncogenes, including YAP, SKP2, and Lin28B13,19,21." (PMID 33628588, 2021). "With the exception of SKP2 and CDKN1A, expression of each of these genes was significantly elevated in ER+ breast cancers with PRR11 copy number gain/amplification in the METABRIC and TCGA dataset." (PMID 33127913, 2020). "To confirm this data, we also measured the expression of Skp2 downstream targets, including p57 and FOXO1, in breast cancer cells treated with various doses of diosgenin for 72 hours." (PMID 32626765, 2020). "SKP2 promoted cell proliferation, inhibited cell apoptosis and enhanced the response to DNA-damage via PDCD4 suppression in breast cancer." (PMID 30760284, 2019). "In addition, we also found increased phosphorylated DNA-PK protein levels in SKP2 overexpressed breast cancer cells compared with control cells after radiation, implying that SKP2 may also participate in DNA-damage repair by involving in non-homologous end joining (NHEJ)." (PMID 30760284, 2019). "To understand the correlation of SKP2 and PDCD4, we performed Western blot and IHC to determine the expression of these proteins in human breast cancer samples and para-carcinoma samples." (PMID 30760284, 2019). "Skp2 SCF complex is an E3 ligase that mediates Akt ubiquitination and activation upon EGF stimulation, leading to the promotion of breast cancer development." (PMID 30413706, 2018). "The results revealed that β-lap down-regulated Skp2 and DEK expression in MCF-7 and MDA-MB-231 breast cancer cell lines." (PMID 28578385, 2017).